CYP4F2 (cytochrome P450 family 4 subfamily F member 2)
Description:
A cytochrome P450 monooxygenase involved in the metabolism of various endogenous substrates, including fatty acids, eicosanoids and vitamins. Mechanistically, uses molecular oxygen inserting one oxygen atom into a substrate, and reducing the second into a water molecule, with two electrons provided by NADPH via cytochrome P450 reductase (CPR; NADPH-ferrihemoprotein reductase). Catalyzes predominantly the oxidation of the terminal carbon (omega-oxidation) of long- and very long-chain fatty acids. Displays high omega-hydroxylase activity toward polyunsaturated fatty acids (PUFAs). Participates in the conversion of arachidonic acid to omega-hydroxyeicosatetraenoic acid (20-HETE), a signaling molecule acting both as vasoconstrictive and natriuretic with overall effect on arterial blood pressure. Plays a role in the oxidative inactivation of eicosanoids, including both pro-inflammatory and anti-inflammatory mediators such as leukotriene B4 (LTB4), lipoxin A4 (LXA4), and several HETEs. Catalyzes omega-hydroxylation of 3-hydroxy fatty acids. Converts monoepoxides of linoleic acid leukotoxin and isoleukotoxin to omega-hydroxylated metabolites. Contributes to the degradation of very long-chain fatty acids (VLCFAs) by catalyzing successive omega-oxidations and chain shortening. Plays an important role in vitamin metabolism by chain shortening. Catalyzes omega-hydroxylation of the phytyl chain of tocopherols (forms of vitamin E), with preference for gamma-tocopherols over alpha-tocopherols, thus promoting retention of alpha-tocopherols in tissues. Omega-hydroxylates and inactivates phylloquinone (vitamin K1), and menaquinone-4 (MK-4, a form of vitamin K2), both acting as cofactors in blood coagulation.
Synonyms: CPF2
Tractability: Small molecule: it belongs to a druggable protein family. Antibody: UniProt places it where antibodies can reach, with high confidence. PROTAC: ubiquitination databases record sites on it; its protein half-life has been measured; a small molecule that binds it is known.
Target class: Cytochrome P450 family 4; Cytochrome P450 4F2; Enzyme; Cytochrome P450 family 4F; Cytochrome P450
Gene: Protein-coding gene on chromosome 19 (15,877,893 to 15,900,528, reverse strand). Ensembl gene ENSG00000186115.
Subcellular location: Microsome membrane; Endoplasmic reticulum membrane
Pathways (Reactome):
Metabolism: Eicosanoids; Fatty acids; Miscellaneous substrates; Synthesis of (16-20)-hydroxyeicosatetraenoic acids (HETE); Synthesis of Leukotrienes (LT) and Eoxins (EX)
Gene Ontology:
Molecular function: alkane 1-monooxygenase activity; alpha-tocopherol omega-hydroxylase activity; arachidonate epoxygenase activity; arachidonate omega-hydroxylase activity; leukotriene-B4 20-monooxygenase activity; long-chain fatty acid omega-hydroxylase activity; oxidoreductase activity, acting on paired donors, with incorporation or reduction of molecular oxygen, NAD(P)H as one donor, and incorporation of one atom of oxygen; oxidoreductase activity, acting on paired donors, with incorporation or reduction of molecular oxygen, reduced flavin or flavoprotein as one donor, and incorporation of one atom of oxygen; protein binding; 20-aldehyde-leukotriene B4 20-monooxygenase activity; 20-hydroxy-leukotriene B4 omega oxidase activity; monooxygenase activity; fatty acid omega-hydroxylase activity; heme binding; iron ion binding; oxidoreductase activity, acting on paired donors, with incorporation or reduction of molecular oxygen; very long-chain fatty acid omega-hydroxylase activity
Biological process: arachidonate metabolic process; epoxygenase P450 pathway; fatty acid omega-oxidation; leukotriene B4 catabolic process; long-chain fatty acid metabolic process; menaquinone catabolic process; negative regulation of icosanoid secretion; omega-hydroxylase P450 pathway; phylloquinone catabolic process; positive regulation of icosanoid secretion; pressure natriuresis; regulation of blood pressure; renal water homeostasis; sodium ion homeostasis; very long-chain fatty acid metabolic process; vitamin E metabolic process; vitamin K catabolic process; xenobiotic metabolic process; blood coagulation; icosanoid metabolic process; leukotriene metabolic process
Cellular component: apical plasma membrane; cytoplasm; intracellular membrane-bounded organelle; endoplasmic reticulum membrane
Genetic constraint (gnomAD): Loss-of-function variants: 58 observed, 60.3 expected, observed/expected ratio (o/e) 0.96, 90% interval 0.78 to 1.2. The upper end of that interval is the gene's LOEUF score, 1.2, which puts it in group 5 of 6, group 1 being the genes least tolerant of losing a copy. Missense variants: 616 observed, 695.04 expected, observed/expected ratio (o/e) 0.89, 90% interval 0.83 to 0.95. Synonymous variants: 287 observed, 261.72 expected, observed/expected ratio (o/e) 1.1, 90% interval 1 to 1.21.
Homologues: Orthologues: chimpanzee CYP4F2 (99% identical), mouse Cyp4f15 (80% identical), mouse Cyp4f14 (80% identical), rat Cyp4f1 (80% identical), rat Cyp4f40 (80% identical), mouse Cyp4f40 (78% identical), rat Cyp4f4 (77% identical), tropical clawed frog cyp4b1.5 (44% identical), tropical clawed frog cyp4b1.2 (44% identical), tropical clawed frog XB5810926 (42% identical), zebrafish cyp4t8 (38% identical), Drosophila melanogaster Cyp4c3 (33% identical), and 28 more. Paralogues in human: CYP4F3 (88% identical), CYP4F11 (87% identical), CYP4F12 (82% identical), CYP4F8 (81% identical), CYP4F22 (65% identical), CYP4A11 (45% identical), CYP4A22 (44% identical), CYP4B1 (43% identical), CYP4X1 (40% identical), CYP4Z1 (38% identical), CYP4V2 (33% identical), CYP19A1 (23% identical).
Diseases named in the same sentence as CYP4F2 in open-access papers:
CYP4F2 is named in the same sentence as 58 diseases in open-access papers, as found by Europe PMC text mining. Sharing a sentence is not in itself a finding about the gene and the disease. The quoted sentences say what the papers report.
Hypertension (17 papers, 2011 to 2025). The presence of chronic increased pressure in the systemic arterial system. "have proved that rs1558139 and rs2108622 of CYP4F2 are associated with hypertension, and the association between rs1558139 and hypertension is particularly strong in men." (PMID 36998451, 2023). "The presence of SNPs in VKORC1 or CYP4F2 genes significantly increased the risk of ischemic stroke in the context of smoking, arterial hypertension, and carotid plaque burden." (PMID 37653796, 2023). "Nonetheless CYP4F22 and CYP4F2 are described as paralogs and genetic variants in the CYP4F2 were associated with hypertension." (PMID 32425885, 2020). "Genetic polymorphisms in CYP4F2 were also found in Chinese, South India, Australian, and American patients and were associated with an increased incidence of hypertension and both ischemic and hemorrhagic strokes." (PMID 31514409, 2019). "Only four case-control studies were enrolled to perform the male/female subgroup analysis for the association between CYP4AF2 rs1558139 and hypertension risk, while six studies were enrolled for CYP4F2 rs2108622." (PMID 29426278, 2018). "Additional case-control studies are needed to further confirm the role of CYP4F2 rs2108622 in hypertension risk." (PMID 29426278, 2018). "Several studies have also associated CYP4F2 expression with inflammatory disorders such as celiac disease and Crohn's disease and other diseases like cardiovascular diseases, hypertension and stroke." (PMID 24759732, 2014). "A functional regulatory CYP4F2 haplotype has also been associated with increased susceptibility to hypertension and myocardial infarction in Chinese and Japanese population, respectively." (PMID 21639946, 2011). "Furthermore, studies show that SNPs of the CYP4F2 gene are associated with various diseases, such as hypertension, cerebral infarction, myocardial infarction, and metabolic syndrome." (PMID 36634101, 2023). "C/T genotype of CYP4AF2 rs1558139 may be linked to the decreased risk of hypertension in the male patients of Asian populations, while CYP4F2 rs2108622 is likely associated with reduced susceptibility to CAD." (PMID 29426278, 2018). "Notably, human mutations in CYP450 hydroxylase enzymes, particularly CYP4A11 and CYP4F2, are linked with increased prevalence of ischemic stroke and hypertension, especially in males, while certain single nucleotide polymorphisms in CYP4F2 are associated with decreased 20-HETE production." (PMID 34819839, 2021). "CYP3A4, APOA2, PPARG, ALOX, and CYP4F2, proteins related to lipid homeostasis affect the occurrence of hypertension, and PTGER2, ALOX5, LTF, ITGB, and GATA3 relate to the inflammatory and immune response in glomeruli." (PMID 30809144, 2019). "Emerging evidence demonstrates that several SNPs in CYP4F2 and CYP4A11 are associated with hypertension and stroke in several populations." (PMID 31514409, 2019). "Variants in CYP4F2 and CYP4A11 have been repeatedly linked to hypertension, stroke, and cardiovascular disease." (PMID 31514409, 2019). "This review summarizes recent genetic variants in CYP4F2, and CYP4A11 influencing 20-HETE production and discusses the role of 20-HETE in hypertension and the susceptibility to the onset, progression, and prognosis of ischemic and hemorrhagic strokes." (PMID 31514409, 2019). "Systemic elevation of 20-HETE levels in transgenic mice with constitutive CYP4F2 overexpression in renal tubular cells has been reported to result in hypertension and hyperglycemia including attenuated GSIS53." (PMID 29330456, 2018). "Many of these studies have discovered an association between some of these SNPs and the susceptibility to hypertension and coronary artery disease, making CYP4A11 and CYP4F2 reasonable candidate genes for altering the risk of CVD." (PMID 29484037, 2018).
Hypertension (continued). "In CYP4F2 gene, a functional haplotype block represented by rs3093105 was found to be associated with urinary 20-hydroxyeicosatetraenoic acid (20-HETE) and hypertension in Chinese individuals, while rs2074902 in the haplotype block and rs3093158 were found to be associated with Crohn's disease." (PMID 25126975, 2014). "As a metabolite of arachidonic acid (AA), partly by CYP4F2 protein, 20-HETE induces the transcription of ACE (angiotensin-converting enzyme) gene through stimulating the NF-ΚB pathway and contributes to the pathophysiology of hypertension." (PMID 29426278, 2018).
ischemic stroke (9 papers, 2013 to 2025). A stroke disorder caused by obstruction of blood flow to the brain, due to thrombotic (local blood clot formation) or embolic (due to a blood clot or other material traveling from another site) event. "Studies have also indicated a significant association between CYP4F2 polymorphisms and a variety of diseases, including ischemic stroke and various other cardiovascular and cerebrovascular diseases." (PMID 36998451, 2023). "For almost all variables, the presence of VKORC1 or CYP4F2 mutations significantly increased the risk of ischemic stroke." (PMID 37653796, 2023). "In Japanese men, the presence of the CYP4F2 rs2108622 G allele was associated with an increased risk of ischemic stroke." (PMID 31514409, 2019). "This is the first study on patients with ischemic stroke that has examined the role of polymorphisms in the VKORC1, CYP4F2, and GGCX genes together." (PMID 37653796, 2023). "Ischemic stroke patients who have both rs9333025 GG (CYP4A11) and rs2108622 GG (CYP4F2) variants have higher plasma 20-HETE levels." (PMID 31514409, 2019). "Of these IL-1α, CYP11B2, ESR1 (PVUII), α ADD1, TNF α (G488A), CYP4F2, MDR-1 and t-PA (I/D) were found to be significantly associated with ischemic stroke." (PMID 23505425, 2013). "Besides that, V433M and additional CYP4F2 alleles which do not lead to amino acid exchanges were associated with ischemic stroke and cerebral infarction in Swedish males, the Han Chinese population and a Japanese cohort." (PMID 40858268, 2025). "The VKORC1 rs9923231 and CYP4F2 rs2108622 polymorphisms may increase the risk of ischemic stroke in patients without a determined embolic source." (PMID 37653796, 2023). "Polymorphisms in the VKORC1 and CYP4F2 genes may increase the risk of ischemic stroke in patients without a determined embolic source." (PMID 37653796, 2023). "The involvement of CYP2U1 in the metabolism of LTB4 could have strong physiological consequences in cerebral pathological events including ischemic stroke because CYP2U1 is predominantly expressed in the brain whereas CYP4F2/4F3 are mainly expressed in liver and neutrophiles." (PMID 36498943, 2022). "In contrast, ischemic stroke patients with both CYP4A11 (rs9333025) and CYP4F2 (rs2108622) SNPs exhibit elevated plasma 20-HETE levels." (PMID 31514409, 2019).
Stroke (7 papers, 2013 to 2023). Sudden impairment of blood flow to a part of the brain due to occlusion or rupture of an artery to the brain. "Polymorphisms in the VKORC1 (−1639G > A) m/m genotype, the CYP4F2 (1347C > T) w/m and m/m genotypes, and history of MI were also linked to stroke, but following Bonferroni correction, the P value threshold was slightly exceeded." (PMID 37653796, 2023). "The VKORC1 and CYP4F2 homozygous genotypes were also more frequent in stroke patients and increased the risk of stroke when they were found in patients with specific comorbidities or conditions." (PMID 37653796, 2023). "The VKORC1 and CYP4F2 homozygous genotypes were associated with an increased risk of stroke, even though the threshold for statistical significance was slightly exceeded in the multivariate model." (PMID 37653796, 2023). "In male patients, four of the 34 SVD-associated genes were unique to that specific stroke cause: CYP4F2, GP1BA, solute carrier family four, member one (SLC4A1), and F13A1, which was also uniquely expressed in the male cohort." (PMID 33193047, 2020). "A large urban-based population study in Sweden suggested there may be an increased risk of stroke, especially in males in the presence of the CYP4F2 rs2108622 (V433M) variant." (PMID 31514409, 2019). "Multiple variants in the SLCO1B1, PRIM1, APOB, TYK2, TSEN15, CYP4F2, and MST1 genes were previously suggested as risk factors for stroke with p-values < 1.0 × 10−5 in a GWAS on German pediatrics." (PMID 37895268, 2023). "The VKORC1 −1639G > A mutant and CYP4F2 1347C > T m/m genotypes were more frequently encountered in the stroke group, although in the case of CYP4F2 m/m, the threshold for statistical significance was slightly exceeded." (PMID 37653796, 2023). "The production of 20-HETE is elevated after the onset of both ischemic and hemorrhagic strokes; on the other hand, subjects with genetic variants in CYP4F2 and CYP4A11 that reduce 20-HETE production are more susceptible to stroke." (PMID 31514409, 2019). "The available evidence seems to suggest that reduced 20-HETE levels may predispose to the development of stroke, although alterations in 20-HETE production associated with many of the human CYP4F2 and CYP4A11 SNPs have not been defined." (PMID 31514409, 2019).
coronary artery disease (6 papers, 2014 to 2024). "We observed that CYP4F2 interacted with the presence of ischemic heart disease increasing the risk of plaque development in the carotid artery, femoral artery, or any of the two." (PMID 32698322, 2020). "The interaction between the VKORC and CYP4F2 polymorphisms and ischemic heart disease is more relevant for the prediction of carotid artery plaque formation than that of femoral artery plaques." (PMID 32698322, 2020). "In light of this, our findings emphasizing the effect of VKORC1 and CYP4F2 on increasing the risk of plaque development once ischemic heart disease is already present are noteworthy." (PMID 32698322, 2020). "The purpose of this study was to investigate whether common single nucleotide polymorphisms in the CYP4A11 and CYP4F2 genes are associated with susceptibility to coronary artery disease in Russian population." (PMID 29484037, 2018). "Thus, we have documented that CYP4F2 and VKORC1 polymorphisms boost the proinflammatory plaque environment (observed indirectly through the presence of ischemic heart disease), increasing the risk of plaque development." (PMID 32698322, 2020). "Enzymes CYP4A11 and CYP4F2 are involved in biosynthesis of vasoactive 20-hydroxyeicosatetraenoic acid and may contribute to pathogenesis of coronary artery disease (CAD)." (PMID 29484037, 2018).
diabetes (6 papers, 2014 to 2025). "Higher concentration of CYP4F2 in patients with diabetes might be associated with higher extent of inflammatory processes as compared to the patients without diabetes." (PMID 32081968, 2020). "Patients with diabetes users of clopidogrel have a higher CYP4F2 concentration than non-diabetic patients." (PMID 32081968, 2020). "Patients with diabetes, ticagrelor users tended to have higher CYP4F2 concentration than non-diabetic patients." (PMID 32081968, 2020). "The CYP4F2 concentration was lower in non-diabetic patients that used clopidogrel compared to patients with diabetes (p = 0.037)." (PMID 32081968, 2020). "The results of this study demonstrated that CYP4F2 and 20-HETE may have a significant role in patients with diabetes and in users of dual antiplatelet therapy." (PMID 32081968, 2020). "Also, patients with diabetes users of ticagrelor tended to have a higher concentration of CYP4F2 in blood plasma than non-diabetics." (PMID 32081968, 2020).
metabolic syndrome (5 papers, 2014 to 2023). A cluster of metabolic risk factors for CARDIOVASCULAR DISEASES and TYPE 2 DIABETES MELLITUS. "A recent study reported an association between CYP4F2 V433M polymorphisms and metabolic syndrome in cohort of Swedish male cardiovascular patients." (PMID 24759732, 2014). "Polymorphism in the human 20-HETE synthase CYP4F2 is associated with metabolic syndrome phenotypes." (PMID 34943862, 2021).
celiac disease (4 papers, 2010 to 2015). An autoimmune genetic disorder with an unknown pattern of inheritance that primarily affects the digestive tract. "A C5a receptor antagonist ameliorates pathology in this model, and genetic association studies link variants of the CYP4F2 and CYP4F3 genes with celiac disease in humans." (PMID 26613087, 2015). "Neutrophils and colonic mucosa from patients with inflammatory bowel disease have reduced LTB4 hydroxylase activity, and genetic association studies link variants of the CYP4F2 and CYP4F3 genes with celiac disease and Crohn's disease." (PMID 26613087, 2015). "Recent reports have shown the expression of CYP4F2 and CYP4F3 genes in the colon of patients with inflammatory celiac disease." (PMID 26114549, 2015).
hepatocellular carcinoma (4 papers, 2019 to 2025). A malignant tumor that arises from hepatocytes. "Recent studies show that CYP4F2 expression is related to hepatocellular carcinoma, NSCLC and breast cancer." (PMID 40858268, 2025). "Other findings suggest that CYP4F2 is downregulated in hepatocellular carcinoma and that low expression of CYP4F2 is correlated with reduced patient survival." (PMID 40858268, 2025). "A study focusing on P450 family 4 gene expression in human hepatocellular carcinoma revealed that CYP4F2 expression is a favourable prognostic factor suggesting a potential predictive diagnostic role." (PMID 40858268, 2025). "have confirmed that low expression of CYP4F2 may contribute to the progression of hepatocellular carcinoma (HCC) and decrease survival rates due to its involvement in various metabolic pathways." (PMID 36998451, 2023). "Evaluation of the CYP4 expression profile in hepatocellular carcinoma (HCC) showed that CYP4F2, CYP4F12, and CYP4V2 mRNA levels were negatively correlated with cell-cycle-associated genes, suggesting that these CYP4 genes are favorable prognostic factors in HCC." (PMID 31480463, 2019).